S100P (S100 calcium binding protein P)
Description:
May function as calcium sensor and contribute to cellular calcium signaling. In a calcium-dependent manner, functions by interacting with other proteins, such as EZR and PPP5C, and indirectly plays a role in physiological processes like the formation of microvilli in epithelial cells. May stimulate cell proliferation in an autocrine manner via activation of the receptor for activated glycation end products (RAGE).
Synonyms: MIG9
Tractability: Antibody: its Gene Ontology location is reachable by antibodies, with high confidence. PROTAC: ubiquitination databases record sites on it; its protein half-life has been measured.
Gene: Protein-coding gene on chromosome 4 (6,693,878 to 6,697,170, forward strand). Ensembl gene ENSG00000163993.
Subcellular location: Nucleus; Cytoplasm; Cell projection, microvillus membrane
Subcellular location (Human Protein Atlas): Nucleoplasm
Pathways (Reactome):
Immune System: Neutrophil degranulation
Gene Ontology:
Molecular function: cadherin binding; calcium-dependent protein binding; protein binding; protein homodimerization activity; calcium ion binding; magnesium ion binding; identical protein binding; transition metal ion binding
Biological process: endothelial cell migration
Cellular component: cytoplasm; extracellular exosome; nucleoplasm; nucleus; extracellular region; secretory granule lumen; microvillus membrane
Genetic constraint (gnomAD): Loss-of-function variants: 7 observed, 5.17 expected, observed/expected ratio (o/e) 1.35, 90% interval 0.74 to 1.91. That is too few expected variants to judge how well the gene tolerates losing a copy. Missense variants: 122 observed, 126.85 expected, observed/expected ratio (o/e) 0.96, 90% interval 0.83 to 1.12. Synonymous variants: 48 observed, 50.99 expected, observed/expected ratio (o/e) 0.94, 90% interval 0.75 to 1.2.
Homologues: Orthologues: macaque S100P (100% identical), chimpanzee S100P (99% identical), dog S100P (81% identical), rabbit S100P (80% identical), tropical clawed frog s100p (63% identical). Paralogues in human: S100A1 (52% identical), S100Z (52% identical), S100B (47% identical), S100A12 (42% identical), S100A4 (41% identical), S100A10 (40% identical), S100A2 (40% identical), S100A5 (40% identical), S100A11 (37% identical), S100A9 (36% identical), S100A8 (34% identical), S100A6 (33% identical), and 9 more.
Diseases named in the same sentence as S100P in open-access papers:
S100P is named in the same sentence as 120 diseases in open-access papers, as found by Europe PMC text mining. Sharing a sentence is not in itself a finding about the gene and the disease. The quoted sentences say what the papers report.
pancreatic cancer (54 papers, 2006 to 2025). "Overall, the proteomic studies revealed the association of radixin, moesin, c14orf166, S100P and hemopexin in LN metastasis in pancreatic cancer." (PMID 39195316, 2024). "Our study suggested a potential association between S100P and the restructuring of the tumor microenvironment in pancreatic cancer." (PMID 37853345, 2023). "At the single-cell level, S100P has been found to be closely associated with the TME of pancreatic cancer, as demonstrated by the results of CRA001160 and GSE154778 datasets." (PMID 37853345, 2023). "The upregulation of S100P has been implicated in the immune dysfunction of pancreatic cancer, particularly in CD8 + T cells." (PMID 37853345, 2023). "This study found that S100P was differentially expressed in pancreatic cancer and was associated with poor prognosis (P < 0.05)." (PMID 37853345, 2023). "Our findings indicated that S100P can potentially contribute to the immunosuppressive microenvironment associated with pancreatic cancer." (PMID 37853345, 2023). "To elucidate the potential of S100P as a pancreatic cancer immunotherapy, we analyzed the association between S100P expression and seven classic immune checkpoints in the TCGA-PAAD and E-MTAB-6134 cohorts." (PMID 37853345, 2023). "Because of its high expression in pancreatic tumors, S100P is clinically used as a diagnostic marker of pancreatic ductal adenocarcinoma." (PMID 37627239, 2023). "Increased S100P levels have been reported in liver, skin, endometrial, colon, and pancreatic cancers, and have been indirectly implicated in promoting carcinogenesis and cancer metastasis in animal models." (PMID 26320193, 2015). "The rank average meta-analysis method identifies S100P as the top pancreatic cancer gene, which has been implicated in several studies." (PMID 23365541, 2012). "Silencing of S100P decreases pancreatic cancer cell growth, motility, invasion, and survival in vitro, whereas S100P overexpression increases pancreatic cancer cell aggressiveness and is associated with increased pancreatic tumor growth and metastasis in vivo." (PMID 22626610, 2012). "The protein products from AGR2, CEAMAN6, GNMT, PDIA2, POSTN, RBPJL and S100P have been reported as potential diagnostic and prognostic biomarkers for pancreatic cancer or have demonstrated to be involved in either pancreatic cancer, initiation, migration, invasion, metastasis, or chemoresistance." (PMID 36812168, 2023). "Moreover, we identified eight DNA methylation probes of S100P potentially associated with the TME in pancreatic cancer, as these methylation sites were positively correlated with CD8 + T cells." (PMID 37853345, 2023). "Receptor for advanced glycation end products (RAGE), a major extracellular binding target of S100P, has been associated with S100P-mediated cancer progression by triggering the oncogenic signaling pathway microRNA-155 and NF-κB in colon and pancreatic cancers, respectively." (PMID 26320193, 2015). "The relationship between S100P and the tumor environment is mainly based on observed correlations, and further mechanistic studies are needed to establish causation and fully elucidate the role of S100P in restructuring the tumor microenvironment in pancreatic cancer." (PMID 37853345, 2023). "Circ_0092314 can act as a sponge for miR-671, leading to increased expression of S100P protein, which in turn induces epithelial–mesenchymal transition in pancreatic cancer cells and promotes pancreatic cancer development." (PMID 41228362, 2025). "Ectopic expression of S100P in pancreatic cancer results in higher tumor growth and metastasis, while the stable silencing results in reduced tumor growth, secondary metastasis and improved sensitivity of cancer cells towards chemotherapy." (PMID 40420099, 2025). "We have previously reported that the S100P gene is upregulated in a sample set of poorly differentiated human pancreatic cancers." (PMID 39125057, 2024).
pancreatic cancer (continued). "S100P is highly expressed in pancreatic cancer and is reported to be involved in proliferation and metastasis." (PMID 38842658, 2024). "Consistent with prior literature, we observed significantly elevated levels of RAGE ligands—HMGB1, S100A2, and S100P—in both human and murine pancreatic cancer cell lines relative to normal pancreatic tissue." (PMID 39796649, 2024). "To test this, we stimulated cells with RAGE ligands observed to be upregulated in human pancreatic cancer, including S100P, S100A2, and HMGB1." (PMID 39796649, 2024). "S100P has been shown to enhance cell proliferation and migration in pancreatic cancer Panc-1 cells through a RAGE-dependent mechanism." (PMID 39796649, 2024). "RAGE inhibitors, primarily through direct inhibition of the RAGE ligand S100P, have shown antitumor activity in preclinical models of pancreatic cancer." (PMID 39796649, 2024). "We argue that the in-depth study of S100P can provide crucial insights and serve as the basis for the development of pancreatic cancer therapy." (PMID 37853345, 2023). "After conducting experiments and analyzing data, it was found that S100P expression is elevated in pancreatic cancer at both cellular and protein levels." (PMID 37853345, 2023). "Next, our study aimed to investigate the potential role of S100P in the immune microenvironment of pancreatic cancer." (PMID 37853345, 2023). "In pancreatic cancer cells, S100P stimulates cell proliferation and invasion through the interaction with RAGE." (PMID 37627239, 2023). "RT-PCR results indicated the upregulation of S100P in five pancreatic cancer cell lines, and immunohistochemistry test images revealed higher expression of S100P in pancreatic cancer tissues than in adjacent tissues." (PMID 37853345, 2023). "Numerous studies have demonstrated that S100P is an oncogenic gene involved in many types of tumors, such as breast cancer, gastric cancer, and pancreatic cancer." (PMID 37853345, 2023). "This study aimed to investigate the potential impact of S100P on TME characteristics in patients with pancreatic cancer." (PMID 37853345, 2023). "S100P, a 95-amino-acid member of the S100 protein family, has been previously established to promote pancreatic cancer growth, metastasis, and invasion." (PMID 37853345, 2023). "Our findings demonstrate that S100P is highly expressed in pancreatic cancer and significantly correlates with CD8 + T cells." (PMID 37853345, 2023). "The experimental drug QN-302 is currently in pre-IND development (as of Q1 2023), and its ability to downregulate S100P protein expression supports a role for this protein as a marker of therapeutic response in pancreatic cancer." (PMID 36985425, 2023). "S100P promotes pancreatic cancer growth, survival, and invasion, and its intracellular levels affect resistance to 5-fluorouracil treatment in vitro." (PMID 37848935, 2023). "Various studies have shown that inhibitors targeting S100P can improve the effectiveness of pancreatic cancer therapy." (PMID 37853345, 2023). "We also report transcriptome analyses showing that S100P expression is highly upregulated in tissues from human pancreatic cancer tumors, compared to normal pancreas material." (PMID 36985425, 2023). "Our results revealed diverse expression patterns of S100P across different cancer types, with high expression observed in pancreatic cancer and a correlation with poor prognosis." (PMID 37853345, 2023). "The main objective of this study is to enhance our understanding of the immunomodulatory effects of S100P in pancreatic cancer, and potentially leverage its role in improving the effectiveness of immunotherapy." (PMID 37853345, 2023). "As far as we acknowledge, this study was the first comprehensive analysis to investigate the potential role of S100P in the immune microenvironment of pancreatic cancer." (PMID 37853345, 2023).
pancreatic cancer (continued). "Although further studies are necessary to validate these findings, emerging evidence portrays S100P as a probable player in the immune microenvironment and response to pancreatic cancer immunotherapy." (PMID 37853345, 2023). "In vitro RT-PCR validated upregulated S100P expression across all five pancreatic cancer cell lines, and IHC confirmed high S100P levels in pancreatic cancer tissues (P < 0.05)." (PMID 37853345, 2023). "S100P is highly expressed in various solid tumors and associated with poor prognosis in CRC, breast cancer, pancreatic cancer, cholangiocarcinoma lung cancer, and ovarian cancer." (PMID 36338624, 2022). "S100P was shown to be highly expressed in pancreatic cancer, adult rhabdomyosarcoma, colorectal cancer, and breast cancer." (PMID 36177001, 2022). "Cromolyn inhibited the NF-κB pathway in pancreatic cancer with endogenic S100P in vitro and in vivo." (PMID 36613714, 2022). "Small molecule inhibitors of S100P were found have anti-metastatic effects on pancreatic cancer cells." (PMID 35830566, 2022). "S100P is highly expressed in pancreatic tumors, where it regulates multiple intracellular and extracellular processes, including cell proliferation, survival, treatment resistance, and diversity." (PMID 36613714, 2022). "Like the results of transcriptome analysis, qRT-PCR presented the similar trends of S100P, which revealed the S100P involved in the tumorigenesis of pancreatic cancer." (PMID 34654352, 2021). "In this study, we analyzed the important functions of S100P in multiple databases using bioinformatic methods, finding that S100P plays important roles in the immune cell infiltration of pancreatic cancer." (PMID 34654352, 2021). "Although a previous study in pancreatic cancer has shown that S100P contributes to the aggressive nature and EMT features of colon cancer cells, the association of S100P expression with EMT induction in PAAD needs further exploration." (PMID 33842379, 2021). "The activation of the RAGE/HMGB1 axis has similar effects on pancreatic cancer cells as the activation of the RAGE/S100P axis." (PMID 33915939, 2021). "The activation of RAGE by S100P in vitro stimulates cell proliferation and migration in human pancreatic cancer cells." (PMID 33915939, 2021). "S100P is a calcium-binding protein in the S100 family that has been shown to affect pancreatic cancer proliferation, angiogenesis, and metastasis." (PMID 34654352, 2021). "In xenograft mouse models of PDAC, RAGE activation by human S100P promotes the growth of pancreatic tumors." (PMID 33915939, 2021). "The anti-S100P antibody 2H8 was introduced to inhibit S100P-induced proliferation of pancreatic cancer cells and blocked increased survival induced by S100P after gemcitabine treatment." (PMID 32722137, 2020). "S100P is a calcium-binding protein that is highly expressed in pancreatic cancer in the early stages and in advanced, metastatic disease." (PMID 32707527, 2020). "S100P stimulates both cell proliferation and migration of human pancreatic cancer Panc-1 cells, in a RAGE dependent manner." (PMID 33086527, 2020). "•Active hits reduce in vitro cell invasiveness selectively in S100P-expressing pancreatic cancer cells." (PMID 32707527, 2020). "Reports in breast, colon, lung and pancreatic cancers award S100P a key role in cancer initiation predictive of metastatic progression and poor prognosis." (PMID 31767037, 2019). "In fact, S100P is regarded as a potential drug target and the development of anti-S100P specific therapies has been considerably addressed, mainly in pancreatic cancer." (PMID 31767037, 2019). "S100P also plays a key role in the aggressiveness of pancreatic cancer which is likely mediated by its ability to activate RAGE." (PMID 29868478, 2018). "Overexpression of S100P is an early marker of pancreatic cancer, which down-regulates the levels of cytoskeletal proteins, which disrupts the actin cytoskeleton network and changes in the phosphorylation status of cofilin." (PMID 28611293, 2017).
pancreatic cancer (continued). "A member of the family of small calcium binding proteins, S100P can mediate tumor growth and metastasis and is highly expressed in pancreatic cancers but low levels are found in the normal pancreas or with chronic pancreatitis." (PMID 22626610, 2012). "CCE cells produced 3-fold more spheres than control cells and were more invasive, secreted more MMP-9, and overexpressed markers for pancreatic SCs/CSCs (i.e., CXCR4, OCT4, CD44) and S100P, a marker for pancreatic cancer." (PMID 22626610, 2012). "S100P is overexpressed in most pancreatic cancers and plays a major role in tumor aggressiveness and was highly increased in CCE cells." (PMID 22626610, 2012). "Markers for CSCs/SCs or pancreatic cancer, including S100P, OCT4, and CXCR4, were assessed in pancreaspheres." (PMID 22626610, 2012). "Increased level of S100P expression has also been found to correlate with poor survival in breast and lung cancer, and with progression to metastatic disease in pancreatic cancer and prostate cancer." (PMID 21466706, 2011). "In addition to RAGE expression, the expression of the RAGE ligands HMGB1, S100A2, and S100P was significantly upregulated in both human and murine pancreatic cancer cell lines when compared to normal pancreas." (PMID 39796649, 2024). "However, the current literature provides limited insights into the possible role of S100P in the regulation of the TME in pancreatic cancer." (PMID 37853345, 2023). "Furthermore, patients with pancreatic cancer were predominantly enriched in the C3 subtype, in which low expression of S100P was a noteworthy trend." (PMID 37853345, 2023). "Our findings indicated no mutations in the S100P gene in pancreatic cancer patients, but its expression was closely connected to methylation status." (PMID 37853345, 2023). "Additionally, there is a potential for S100P to impact the regulation of pancreatic cancer through DNA hypomethylation." (PMID 37853345, 2023). "Therefore, this study was designed to explore the potential biological mechanisms and regulation of S100P in the pancreatic cancer microenvironment." (PMID 37853345, 2023). "Thus, this study aims to examine the possible role of S100P in the TME of pancreatic cancer in a systematic manner." (PMID 37853345, 2023). "In vivo data revealed that the S100P-derived inhibitor may have therapeutic potential against glioma and pancreatic cancer and may inhibit a variety of RAGE ligands, implying that it could be useful in additional RAGE-related diseases." (PMID 36613714, 2022). "S100P in the S100 calcium-binding protein family is originally isolated from human placenta, and S100P expression is elevated in a variety of tumor cell lines and tumor tissues, including in lung cancer, pancreatic cancer, and breast cancer." (PMID 34745947, 2021). "Here, we found that KLF5 could act as a positive TF with S100P and jointly participate in the malignant biological behavior of pancreatic cancer." (PMID 34654352, 2021). "In this study, we constructed an immune-related prognostic signature based on four immune-related genes (ADA2, TLR1, PTPN6, and S100P) that displayed good predictive ability for overall survival and analyzed the infiltration of corresponding immune cells in patients with pancreatic cancer." (PMID 34654352, 2021). "Prognostic signature containing four IRGs (ADA2, TLR1, PTPN6, S100P) was constructed with good predictive performance; in particular, S100P played a significant role in the immune microenvironment, and tumorigenesis of pancreatic cancer." (PMID 34654352, 2021). "The expression level of S100P is correlated with the rates of cell proliferation, survival, migration and invasion, which makes S100P protein a major promoting factor in the pathogenesis of pancreatic cancer." (PMID 28611293, 2017).